APOE (apolipoprotein E)
Diseases named in the same sentence as APOE in open-access papers (continued):
Sharing a sentence is not in itself a finding about the gene and the disease.
dementia (continued). "APOE ε4 carriage was a significant risk factor for all-cause dementia in MAP [HR (95%CI): 1.99 (1.49, 2.66)] and WHIMS [HR (95%CI): 2.08 (1.89, 2.30)] but not in CHAP-White [HR (95%CI): 1.80 (0.76, 4.29)] or CHAP-Black [HR (95%CI): 1.20 (0.46, 3.15)] cohorts." (PMID 35807939, 2022). "Meanwhile, we found an interaction between PPI use and APOE ε4 genotype for all-cause dementia, and the association was more significant among APOE ε4 heterozygotes." (PMID 36045363, 2022). "Some studies have, however, investigated interactions between single genetic variants (usually APOE ε4) and either single foods or nutrients, or dietary patterns, in relation to either dementia or cognitive function." (PMID 34632537, 2022). "Doing so, we found that APOE ɛ4 had a stronger association with incident dementia in women than men across all amyloid levels." (PMID 35310829, 2022). "For example, we disregarded the fact that APOE genotype has previously been associated with incident dementia." (PMID 36589539, 2022). "We find that APOE alleles distribution varies by ethnic groups, but the alleles have a similar association with dementia across all ethnic groups." (PMID 36477264, 2022). "One study reported that many patients with dementia have at least one ApoE ε4 allele, compared to healthy subjects." (PMID 35328405, 2022). "GRS including APOE predicted dementia in all ethnic groups and was also associated with family history of dementia." (PMID 36477264, 2022). "This suggests that, even though the APOE genotype is associated with dementia, with adequate treatment and cognitive training, the onset of severe cognitive effects can be delayed, improving quality of life." (PMID 36292001, 2022). "Participants who had a family history of dementia or the APOE ε4 allele were considered to be at an increased risk for AD." (PMID 36533177, 2022). "In this context, the ApoE-ε4 carrier status and female sex are well-known risk factors for CD and various forms of dementia, which have been demonstrated to be capable of modulating fatty acid metabolism." (PMID 34980257, 2022). "Considering polygenic risk quintiles in the model and additionally adjusting for APOE ε4 allele status yielded similar associations with dementia risk." (PMID 35711612, 2022). "On this basis, ApoE e4 alleles have been tested in an attempt to find a correlation with COVID-19 severity, as ApoE e4 genotype has been associated with both dementia and delirium." (PMID 35618891, 2022). "This hospital-based case-control study demonstrated the impact of specific diseases/events and the ApoE polymorphism on dementia occurrence." (PMID 36578446, 2022). "A study from the from the French Three-City Study found an interaction between APOE ε4 and high glycemic load (GL) afternoon snacks, and that high afternoon-snack GL was associated with increased dementia and AD risk in APOE-ε4 carriers." (PMID 34632537, 2022). "We investigated several single-nucleotide polymorphisms that were initially associated with suicide risk in dementia older adults and identified the APOE gene alleles." (PMID 36421848, 2022). "Examination of a prospective cohort with 105,949 white individuals revealed that an increase in plasma apoE level from 2.5 to 5 mg/dL was associated with lower dementia risk but when apoE level exceeded 5 mg/dL, the association with dementia risk was inversed." (PMID 35751102, 2022). "As RBD was associated with a higher rate of cognitive decline and dementia in previous studies, we explored a potential association between pRBD and APOE ɛ4 carrier status." (PMID 36245388, 2022). "Multimorbidity significantly interacted with APOE-ε4 carrier status in association with incident dementia." (PMID 36125811, 2022). "PA has shown to be inversely associated with brain amyloid deposition and to a greater extent in APOE ε4 carriers; however, contradictory results have been reported when examining dementia risk as an outcome measure." (PMID 35418852, 2022).
dementia (continued). "There was an association between the western dietary pattern and an increased risk of dementia among APOE ε4 carriers in the fully adjusted model 2 (HR 1.37; 95% CI 1.05–1.78), but not in model 1 (HR 1.28; 95% CI 0.99–1.66)." (PMID 34632537, 2022). "Dementia is associated with many comorbidities while being related to Apolipoprotein E (ApoE) polymorphism." (PMID 36578446, 2022). "Previous studies have reported that FTO is associated with structural brain atrophy in healthy elderly subjects, and a prospective cohort study also found that FTO interacts with apolipoprotein E (APOE) to increase the risk of dementia, especially AD." (PMID 35518355, 2022). "Participants with a family history of dementia or who were APOE e4 carriers were considered at an increased risk for AD." (PMID 36711200, 2022). "We had the preservation to conclude the interaction between the ApoE genotype and comorbidities, as well as the dementia risk related to individual comorbidities in three age groups." (PMID 36578446, 2022). "The associations of sleep problems with dementia and AD were evident mainly among young-old adults (65-74 years) or APOE ε4 carriers." (PMID 34979998, 2022). "These novel APOE models increase the ability to elucidate the mechanisms by which heterozygous APOE genotypes increase risk for AD and dementia." (PMID 35370604, 2022). "The observed associations were independent of the traditional and potential risk factors of dementia, including diet and lifestyle factors, severity of diabetes, frailty, and APOE ε4 genotype." (PMID 35025861, 2022). "For verifying these tentative results, more studies are needed that investigate the association of different types of protein sources with dementia incidence or cognitive performance and consider the APOE-ε4 phenotype." (PMID 35217900, 2022). "In a multi-racial cohort of New York City, APOE ε2/ε3 genotype was associated with an 8x increased risk of dementia of AD-type in African-Americans (self-declared race)." (PMID 36071110, 2022). "A high glycaemic intake, particularly when included in the diet as an afternoon snack, has been associated with increased dementia risk for APOE-e4 carriers." (PMID 36568511, 2022). "Very few studies focus on the impact of the convergence of neuropsychiatric symptoms and APOE ε4 allele on the conversion to dementia in individuals with MCI." (PMID 36292001, 2022). "PCBrainAge captures meaningful heterogeneity of aging: Its acceleration demonstrates stronger associations with clinical AD dementia, pathologic AD, and APOE ε4 carrier status compared to extant epigenetic age predictors." (PMID 35907208, 2022). "The finding of a higher frequency of APOE ε4 allele in this Black population is consistent with studies of African Americans in the US but its association with dementia in these studies has been inconsistent." (PMID 36223334, 2022). "One of the possible explanations is that the ε4 allele of the apolipoprotein E gene is the strongest genetic risk factor for late-onset AD, and it has been identified as a risk factor for other dementia sub-type." (PMID 36514123, 2022). "Among the three alleles of APOE, APOE ε4 allele is more relatable to AD, dementia, memory loss, and so on compared to the APOE ε4 suppressed or knock-out model." (PMID 36501161, 2022). "Coincidently, researchers have found that both NAFLD and dementia share 2 important biological risk factors, apolipoprotein E (APO-E) and adiponectin (ADPN)." (PMID 36204558, 2022). "In this article, we report that asymptomatic individuals at heightened risk of dementia due to their family history, Apolipoprotein-E ɛ4 genotype, and central adiposity have a hub in the right paracentral lobule, which is absent in low-risk groups." (PMID 34030485, 2022). "While the CARDS sample was too small to quantify AD and/or obesity-related polygenic risk hazards, we included family history of dementia as a variable that captures environmental and genetic risk factors beyond APOE ε4." (PMID 35303671, 2022).
dementia (continued). "Previous studies have found that the Blacks are at higher risk for more severe AD symptoms, more likely to have the apolipoprotein E isoform associated with AD development, and more likely to have dementia caused by mixed pathology." (PMID 35130899, 2022). "APOE-ε4 impacts the risk of dementia associated with stroke in patients, and both pre- and post-event dementia were found to be linked to APOE-ε4 homozygosity." (PMID 36421725, 2022). "Compared to the most common APOE ε3/ε3 genotype, each additional copy of the APOE-ε4 allele is associated with a higher risk of AD and a younger mean age of dementia onset." (PMID 36324176, 2022). "Only age, APOE ε4 genotype, and a depression treated with anti-depressants (likely as an indicator of a major depression) were stronger risk factors for all-cause dementia in our study." (PMID 36085081, 2022). "For example, among OXVASC patients with TIA/minor stroke, apolipoprotein E (APOE)-ε4 homozygosity was associated with both pre- and post-event dementia up to five years of follow-up." (PMID 35566762, 2022). "MCI subjects who developed dementia were more likely to have at least one copy of the APOE ε4 allele." (PMID 36292001, 2022). "The ε4 allele of the APOE gene was significantly associated with dementia in both heterozygous (OR = 2.23, 95% CI = 1.16–4.31, p = 0.001, FDR = 0.02) and homozygous (OR = 12.57, 95% CI = 1.41–112.41, p = 0.005, FDR = 0.08) carriage." (PMID 36421848, 2022). "APOE, the gene responsible for producing ApoE, can have multiple alleles predisposing the carrier to dementia." (PMID 36033603, 2022). "The adjusted HR of dementia risk for glucosamine users and APOE ε4 carrier group was 2.75 (95% CI: 2.49–3.04)." (PMID 36514123, 2022). "Of 234 with complete data (48 with dementia), APOE ε4 and greater lifetime physical activity were associated with increased risk of dementia whereas the inverse was found for hypertension." (PMID 36350423, 2022). "Demographic factors such as old age, male, less educated, ApoE-ɛ4 carrier status and slower gait were risk factors for dementia onset in a cognitively healthy sub-cohort." (PMID 35888143, 2022). "The clinical management of these patients must be more intense due to hyperglycemia has been associated with increased risk of dementia and mental disorders in the elderly population depending on the APOE genotype." (PMID 36147576, 2022). "We examined the interactions of other sleep parameters with demographics and APOE ε4 allele on the likelihood of dementia." (PMID 34979998, 2022). "Human studies have identified low plasma apoE values as a significant risk factor for AD and other types of dementia." (PMID 36153580, 2022). "Low plasma ApoE levels are associated with an increased risk of dementia, whereas high levels are associated with an increased risk of ischaemic heart disease and diabetes." (PMID 36291633, 2022). "The APOE ε4 homozygote is a validated risk factor with significant effects, and its HRs of all-cause dementia and AD were 6.93 (95% CI, 6.05–7.92; P < 0.001) and 12.91 (95% CI, 10.59–15.75; P < 0.001) in this study." (PMID 36045363, 2022). "When we included APOE in the Cox regression model with all other risk factors the HR for dementia in Black participants was 1.04 (95%CI 0.80–1.36, p = 0.758) and in South Asians was 1.03 (95%CI 0.78–1.36, p = 0.836)." (PMID 36223334, 2022). "For example, among APOE ɛ4 carriers with moderate amyloid levels, the remaining lifetime risk of dementia at age 65 years was 58% (95% CI 52–65%) for women compared to 44% (95% CI 35–53%) among men." (PMID 35310829, 2022). "α-Syn PFF treatment significantly up-regulated the ApoE protein, whose ε4 genotype in humans regulates α-syn pathology and is associated with an increased risk of dementia in PD and AD." (PMID 36044549, 2022). "APOE ε4-negative subjects had stronger associations between inflammation biomarkers and dementia outcomes than APOE ε4-positive individuals." (PMID 36085081, 2022).
dementia (continued). "Grey matter atrophy has been reported in cognitively healthy individuals positive for amyloid pathology and tau pathology, family history of dementia, and the APOE e4 allele." (PMID 36711200, 2022). "Patterns of remaining lifetime risk of dementia varied considerably by APOE/sex/amyloid group and mirrored those for HRs." (PMID 35310829, 2022). "Although ApoE polymorphism seems to be the riskiest factor for dementia, the effects of the number of ε4 alleles differ." (PMID 36578446, 2022). "Stratification based on the APOE ε4 genotype, a major risk factor for the development of AD, will be required to determine the likelihood of dementia, disease progression, and possible risk for ARIA." (PMID 35964143, 2022). "Accuracy of genetic risk and its association with dementia is improved in all groups by including APOE." (PMID 36477264, 2022). "In sensitivity analyses, APOE ɛ4 (HR 1.68; 95% CI 1.41–2.02, P = 1 × 10–8) and ɛ2 carriership (HR 0.76; 95% CI 0.59–0.97, P = .03) remained associated with incident dementia, after excluding APOE ɛ4/ɛ2 heterozygotes (n = 2015)." (PMID 33532541, 2021). "Firstly, gene polymorphisms of apolipoprotein E, which plays a role in modulating inflammation, have been associated with both psoriasis and dementia." (PMID 32896023, 2021). "We found an association between AD‐PRSs (including 39 and 57 SNPs) and dementia among APOE ɛ4 non‐carriers." (PMID 33532541, 2021). "APOE genotype is associated with early changes (i.e., prior to dementia onset) in brain metabolism, cognition, and neuroimaging measures." (PMID 33939248, 2021). "The increased risk of dementia and AD was further correlated with elevated DNA methylation levels in the promoter region of APOE." (PMID 34831288, 2021). "In line with our data, two recent meta-analyses reported an increased risk of dementia in PD patients who carried the APOE ε4 allele, although regional differences in effect size were noted." (PMID 33613437, 2021). "Parental history of dementia, APOE variant, atrial fibrillation, diabetes, hypertension, and hypercholesterolemia all had strong associations with vascular dementia (p < 4.6×10–6)." (PMID 33682710, 2021). "Dementia incidence was low across all genotype groups, but APOE ε4 and high PRS still increased relative risk." (PMID 34041846, 2021). "This is the first large RCT showing that a multidomain lifestyle intervention facilitated LTL maintenance among subgroups of older people at risk for dementia, including APOE-ε4 carriers." (PMID 33175128, 2021). "Among those aged 70 to 94 years, the 39‐SNPs AD‐PRS was associated with incident dementia in APOE ɛ4 non‐carriers (HR 1.16; 95% CI 1.01–1.34, P = .03), but not in ɛ4 carriers (HR 1.08; 95% CI 0.88–1.33, P = .5)." (PMID 33532541, 2021). "In our study APOE ε4 was significantly associated with both Thal Aβ phases and CERAD neuritic plaque scores, supporting that APOE ε4 exerts its genetic risk on dementia primarily through Aβ neuropathology." (PMID 33613437, 2021). "The PRS enriched the ability of APOE to discern AD with stronger associations than to VD, MD, or all-cause dementia in a prospective community-based cohort." (PMID 32404947, 2021). "They further figured out that FTO's effect on dementia or AD risk mainly was through interaction with the APOE ɛ4 allele." (PMID 34461609, 2021). "Some experience is also gained in the trial setting, where protocols for disclosure of APOE and amyloid test results and dementia risk have been developed, and studies show that biomarker disclosure is not harmful in the short term." (PMID 34635169, 2021). "APOE ɛ4 carriership predicted dementia in the low‐ and middle‐risk tertiles of the 39‐SNPs AD‐PRS, and in all tertiles of the 1e–5 AD‐PRS." (PMID 33532541, 2021). "It is also possible that APOE ε4 carriage is an independent process from dietary aspects in relation to dementia risk." (PMID 33748832, 2021).
dementia (continued). "The 1e–5 AD‐PRS remained associated with incident dementia among APOE ɛ4 non‐carriers after removal of rs7584040 (P = .01), rs11168036 (P = 9 × 10–3), rs143429938 (P = 6 × 10–3), and rs8064326 (P = .01)." (PMID 33532541, 2021). "Further large-scale population-based studies are needed to investigate the associations between other cognitive domains and the APOE ε4 allele in dementia-free Chinese older adults." (PMID 33790814, 2021). "In contrast, people with more years of education seem to have less risk of developing dementia, even if they have well-known dementia genetic risk factors such as APOE ε4." (PMID 34639242, 2021). "We detected elevated levels of both pathological proteins in subjects with dementia, as well as in carriers of APOE ε4 allele, trends that have been described previously." (PMID 33796061, 2021). "It increased dementia risk in a way such that the relative risk of other risk factors including smoking on dementia weakened in APOE ε4 heterozygotes, and even disappeared in ε4 homozygotes." (PMID 34155245, 2021). "Subgroup analysis according to the diagnostic methods for hearing loss, validation strategy for dementia, follow-up duration, and adjustment of apolipoprotein E genotype also showed consistent results (p-values for subgroup differences all > 0.05)." (PMID 34305572, 2021). "Among those aged 95 years or older, APOE ɛ4 carriership only predicted dementia in the low‐risk tertile of the AD‐PRSs." (PMID 33532541, 2021). "PRS effect on dementia risk was modest and delayed compared with APOE ε4, mostly affecting risk after 85 years of age." (PMID 34041846, 2021). "APOE genotype modified the effect of smoking status on dementia risk among women and men in different ways." (PMID 34155245, 2021). "Genetically, people who carry an Apolipoprotein E (APOE) e4 allele are considered to be a high-risk group for dementia." (PMID 34366944, 2021). "Dementia risk was significantly higher among APOE-ε4 allele carriers compared to non-ε4 allele carriers." (PMID 34155245, 2021). "Population attributable risk prediction models suggested that about 40% of dementia cases are attributable to modifiable factors and 7% to apolipoprotein E (ApoE) ε4 allele, the major genetic risk factor for AD." (PMID 34764935, 2021). "In this large, population-based cohort of older adults, participants with ≥1 APOE ε4 alleles received a dementia diagnosis an average of 1 year earlier for Blacks and 2.5 years earlier for Whites compared with non-APOE ε4 carriers." (PMID 34744974, 2021). "Current smokers had a higher risk of dementia among non-APOE-ε4 allele carriers and among individuals within high polygenic risk." (PMID 34155245, 2021). "These apparent similarities should be interpreted with additional caution though, given that none of the cortical changes were significantly steeper in carriers of the APOE e4 allele, which is a well-known risk factor for late-life dementia." (PMID 33398085, 2021). "Cox proportional regression was used to analyze the association of baseline GFRcrcys levels with incident dementia/AD, adjusting age, gender, education years, APOE-ε4, diabetes, hypertension, baseline Mini-Mental State Examination score, and proteinuria." (PMID 33430940, 2021). "In line with this, we found that the AD‐PRS was associated with reduced risk of dementia in APOE ɛ4 carriers, while it was associated with increased risk of dementia in APOE ɛ4 non‐carriers." (PMID 33532541, 2021). "Previous studies also showed that APOE ε2 was associated with an increased neuropathology and decreased risk of dementia." (PMID 33994988, 2021). "Using an additive model, female PD patients carrying the minor allele (T) at SNP rs429358 at APOE, or having an APOE ε4 allele have an ~8-fold increased risk of having a positive family history of more than one family member with dementia." (PMID 33935957, 2021).